EGFR (epidermal growth factor receptor)
Diseases named in the same sentence as EGFR in open-access papers (continued):
Sharing a sentence is not in itself a finding about the gene and the disease.
keratinocyte carcinoma (1 paper, 2024). A skin cancer arising from the keratin-producing cells of the epidermis. "In keratinocyte carcinoma, EGFR signalling inhibition is a potent adjuvant for cancer treatment." (PMID 38317244, 2024).
keratitis (1 paper, 2023). A corneal disease that is characterized by inflammation of the cornea. "Among all TKi in clinical oncology practice, epidermal growth factor receptor inhibitors (EGFRi) have been most commonly reported to be associated with keratitis." (PMID 37424746, 2023). "In the LUX-lung 3 trial for metastatic lung adenocarcinoma with EGFR mutations, the prevalence of keratitis in these patients was 2.2%." (PMID 37424746, 2023).
Kindler syndrome (1 paper, 2019). Kindler syndrome (KS) is the fourth major type of epidermolysis bullosa (EB), besides simplex, junctional and dystrophic forms, and is characterized by skin fragility and blistering at birth followed by development of photosensitivity and progressive poikilodermatous skin changes. "In this study we show that skin and keratinocytes from Kindler syndrome patients have significantly reduced expression levels of the EGFR, resulting in defective EGF-dependent signaling and cell migration." (PMID 30248333, 2019).
lactic acidosis (1 paper, 2025). Metabolic acidosis characterized by the accumulation of lactate in the body. "Recent in vitro research also reported that high glucose and lactic acidosis conditions promoted aggressiveness of fluke-positive CCA cell lines via the EGFR/STAT3-dependent and ALDH1A3/EGFR axis, respectively." (PMID 40918454, 2025).
lactotroph adenomas (1 paper, 2023). "Regarding tyrosine kinases, both preclinical and clinical research has underscored the importance of the EGFR pathway in corticotroph and lactotroph adenomas." (PMID 38275385, 2023).
laryngeal papilloma (1 paper, 2020). "In HPV positive laryngeal papilloma, the activity of PI3K/Akt is significantly upregulated, causing the stimulation of the Epidermal Growth Factor Receptor (EGFR) and consequently, the activation of MAPK/ERK cascade." (PMID 32211411, 2020).
lichen planus (1 paper, 2024). A chronic, recurrent, pruritic inflammatory disorder of unknown etiology that affects the skin and mucus membranes. "From the control group to the erosive lichen planus, there is an ascending trend in EGFR staining." (PMID 38914986, 2024). "The present study concluded that EGFR might probably utilized as a marker for the treatment for erosive type of lichen planus." (PMID 38914986, 2024).
liver tumor (1 paper, 2015). "Of note, inhibition of reactive oxygen species (ROS) production attenuated growth of liver tumor cells, which coincided with decreased EGFR phosphorylation and downregulation of EGFR and TGF-α." (PMID 26729094, 2015).
lupus erythematosus (1 paper, 2024). An autoimmune, connective tissue chronic inflammatory disorder affecting the skin, joints, kidneys, lungs, heart, and the peripheral blood cells. "Two prior reports have linked EGFR TKIs to lupus erythematosus-like eruptions, among which there has only been one case of SCLE." (PMID 39430640, 2024).
lymph node only disease (1 paper, 2008). "Notably, this patient had lymph node only disease and very high EGFR amplification by FISH and normal PTEN." (PMID 18700047, 2008).
lymphatic system disorder (1 paper, 2025). A disease involving the lymphatic part of lymphoid system. "Furthermore, DA showed that Osimertinib was not only significantly associated with Blood and lymphatic system disorders, Gastrointestinal disorders, and Renal and urinary disorders but was also the only EGFR-TKI to yield a positive signal for Cardiac disorders." (PMID 40135231, 2025).
lysosomal storage disease (1 paper, 2018). A metabolic disorder caused by mutations in proteins critical for lysosomal function, including lysosomal enzymes, lysosomal integral membrane proteins, and proteins involved in the post-translational modification and trafficking of lysosomal proteins. "In conclusion, our findings provide novel clues for EGFR pathway targeting-based approaches for MPS IIIB as well as for other lysosomal storage diseases." (PMID 29348482, 2018). "To establish the EGFR contribution to MPS IIIB lysosomal disorder in our cellular model, we evaluated the lysosomal accumulation in the H9C2 sh-CTR and H9C2 sh-NAGLU clones treated with the specific EGFR inhibitor AG1478." (PMID 29348482, 2018).
macular degeneration (1 paper, 2025). Loss of vision in the central portion of the retina (macula), secondary to retinal degeneration. "Notably, defective endosomal EGFR signaling was sufficient to induce deleterious consequences for the health of photoreceptor cells, which showed reduction in POS compared with native rods, similar to the pathogenesis of macular degeneration." (PMID 39937579, 2025).
malabsorption syndrome (1 paper, 2026). A syndrome resulting from the inadequate absorption of nutrients in the small intestine. "Anorexia, malabsorption syndromes, ectopic ACTH, drugs (thiazide diuretics, insulin, granulocyte growth factor, glucocorticoids), antineoplastic drugs (cisplatin, ifosfamide, anti-EGFR agents, mTOR inhibitors, eribulin, abiraterone)." (PMID 41601884, 2026).
megaloblastic anemia (1 paper, 2024). Anemia characterized by the presence of unusually large erythroblasts in the bone marrow called megaloblasts. "However, megaloblastic anemia caused by EGFR TKIs are very rare." (PMID 38448889, 2024).
megaureter (1 paper, 2022). "KEGG analysis also showed that “MAPK signaling”, “AGE–RAGE signaling pathway”, “EGFR tyrosine kinase inhibitor resistance”, and “regulation of actin cytoskeleton” are the major pathways associated with the differentially m6A methylated transcripts in megaureter obstructive uropathy." (PMID 35795641, 2022).
memory (1 paper, 2024). The activities involved in the mental information processing system that receives (registers), modifies, stores, and retrieves informational stimuli. "In APP/PS1 double Tg mice, the EGFR antagonist gefitinib improves memory impairments." (PMID 39434878, 2024).
meningococcal infection (1 paper, 2009). Infections with bacteria of the species neisseria meningitidis. "In this study, we investigated how meningococcal infection differentially modulates host cell motility and EGFR signalling pathways through two independently regulated variants of T4P components." (PMID 19718432, 2009).
Menstrual disorder (1 paper, 2025). Category of disorders related to menstruation. "Interruptions in EGFR signaling have been linked to menstrual disorders, notably abnormal vaginal bleeding." (PMID 40028534, 2025).
mesoblastic nephroma (1 paper, 2025). A solid, unencapsulated tumor of the kidney composed of spindle mesenchymal cells that resemble fibroblasts or muscle cells. "The authors also suggest a potential relationship with mixed and classic mesoblastic nephroma, both carrying EGFR‐KDDs, while it is found very rarely in cellular mesoblastic nephroma, which is considered the renal counterpart of IF, characterized by ETV6::NTRK3 fusion." (PMID 40178433, 2025).
microcephaly (1 paper, 2025). A congenital or acquired developmental disorder in which the circumference of the head is smaller than normal for the person's age and sex. "Our results are consistent with previous studies linking EGFR suppression to impaired NPC proliferation and microcephaly, and atRA exposure to proliferation arrest and prolonged cell cycle G1 phase." (PMID 40147140, 2025).
Middle Ear Cholesteatoma (1 paper, 2013). "In our future study, we will develop animal models of middle ear cholesteatoma in which potential inhibitors of EGFR/PI3K/Akt/cyclinD1 signaling pathway might become more accessible to research." (PMID 24311896, 2013). "To test our hypotheses, firstly we examined the expressions of phosphorylated EGFR (p-EGFR), phosphorylated Akt (p-Akt), cyclinD1, and proliferating cell nuclear antigen (PCNA) in middle ear cholesteatoma and normal EAC skin specimens." (PMID 24311896, 2013).
mixed tumours (1 paper, 2012). "A recent study showed that the overexpression of the epidermal growth factor receptor (EGFR) by malignant epithelial cells might occur early in the carcinogenesis of mixed tumours." (PMID 23193497, 2012).
monoclonal gammopathy of undetermined significance (1 paper, 2020). "We found that bone marrow endothelial cells from patients with MM express high levels of EGFR and HB-EGF, compared with cells from patients with monoclonal gammopathy of undetermined significance, and that overexpressed HB-EGF stimulates EGFR expression in an autocrine loop." (PMID 31936715, 2020).
mucinous lung adenocarcinoma (1 paper, 2020). "Upon treating mucinous lung adenocarcinoma with the EGFR inhibitor gefitinib, the EGFR ligand amphiregulin promotes the binding of IGF-IR to importin-β1 and triggers nuclear localization of IGF-IR, which in turn prevents the induction of apoptosis by gefitinib." (PMID 32493414, 2020).
mucopolysaccharidoses (1 paper, 2021). "GSEA demonstrated that mucopolysaccharidoses, the butyrophilin BTN family, the EGFR/SMRTE pathway, IRF3- mediated induction of type I INF, FOXO-mediated transcription of cell cycle genes, and the ERK pathway were differentially enriched in association with high levels of CYBRD1 expression." (PMID 34594380, 2021).
myoepithelial carcinoma (1 paper, 2020). "Our case is unique because we presented the first clinical evidence of EGFR-TKI targeted therapy for myoepithelial carcinoma." (PMID 32505185, 2020).
myxoid liposarcoma (1 paper, 2022). A liposarcoma characterized by the presence of round non-lipogenic primitive mesenchymal cells and small signet ring lipoblasts within a myxoid stoma with a branching vascular pattern. "Tumor-associated macrophages (most are M2 macrophages) accelerated cell motility and invasion of myxoid liposarcoma (MLS) cells by activating the EGFR/PI3K/AKT signaling pathway." (PMID 35237300, 2022).
nail infection (1 paper, 2024). An infectious process affecting the nail. "In addition, skin and nail infections secondary to HP therapy appeared histologically similar to EGFR associated cutaneous toxicities, suggesting some shared pathologic process." (PMID 37833451, 2024).
Neonatal sepsis (1 paper, 2021). Systemic inflammatory response to infection in newborn babies. "EGFR prevents the translocation of gut-residing pathogenic and cancer-associated protein kinases and is a key target for late-onset neonatal sepsis and cancer." (PMID 34483900, 2021).
nephrosclerosis (1 paper, 2020). Hardening of the kidney due to infiltration by fibrous connective tissue (fibrosis), usually caused by renovascular diseases or chronic hypertension. "Compared with epidermal growth factor receptor and cytotoxic granule protein, macrophage activating factors seems to mediate the incident of osimertinib induced nephrosclerosis." (PMID 33584816, 2020).
neuronal tumor (1 paper, 2023). Neuronal brain tumors are an uncommon group of central nervous system tumors that arise from cells with neuronal differentiation. "In pediatric-type diffuse gliomas and glioneuronal and neuronal tumors, alterations in EGFR and TERT were correlated with a poor prognosis, respectively." (PMID 36998447, 2023).
neuropathic pain (1 paper, 2025). Chronic pain caused by damage to nerve fibers. "The epidermal growth factor receptor (EGFR), which was also downregulated in our analysis, has been associated with pain signaling, and its inhibition has shown pain relief in neuropathic pain patients." (PMID 40173182, 2025).
obstructive sleep apnea (1 paper, 2022). "A non-coding genetic variant rs6593210 which disrupts the hypoxia-response element (HRE) also transcriptionally regulates EGFR in patients with COPD and obstructive sleep apnea." (PMID 35634326, 2022).
odontogenic tumors (1 paper, 2011). "The expression of EGFR by odontogenic tumors could be an interesting approach to explore." (PMID 21968082, 2011).
opisthorchiasis (1 paper, 2025). Infection with flukes of the genus Opisthorchis. "Thus, our study revealed for the first time the involvement of EGFR-associated cellular pathways in the development of BilIN in opisthorchiasis in patients, in laboratory animals, and in cell models." (PMID 40732668, 2025). "Nevertheless, we demonstrated the activation of EGFR signaling pathways in the development of biliary intraepithelial neoplasia in opisthorchiasis." (PMID 40732668, 2025). "In conclusion, a significant increase in EGFR positive staining was observed in both the experimental opisthorchiasis model and patient liver samples." (PMID 40732668, 2025). "Thus, both in the experimental opisthorchiasis model and in patient samples, a significant increase in EGFR content was revealed." (PMID 40732668, 2025). "To investigate the EGFR content during O. felineus infection, we performed specific staining for EGFR and EGFRp in the livers of Syrian hamsters (M. auratus), a common experimental model of opisthorchiasis." (PMID 40732668, 2025).
optic neuritis (1 paper, 2024). Optic neuritis is inflammation of the optic nerve, the nerve that carries the visual signal from the eye to the brain.The conditionmay cause sudden, reduced vision in the affected eye(s). "Anticancer drugs which target to epidermal growth factor receptor can inhibit corneal reparation and induce ocular toxicity, indicating that MS may also affect the occurrence of optic neuritis through non-inflammatory ways." (PMID 38375484, 2024).
oral candidiasis (1 paper, 2022). Infection of the mucosal lining of the mouth with the fungus Candida albicans. "Inhibition of EGFR in mouse models of oral candidiasis reduces IL-1β and CXCL1, suggesting EGFR may be the initial receptor responsible for CXCL1-mediated neutrophil recruitment." (PMID 36012793, 2022).
orofacial cleft (1 paper, 2021). A disorder of facial skeleton that is characterized by cleft lip and/or cleft palate that result in feeding, speech and hearing problems caused by failures during development. "Therefore, it is important to identify different tissue factors, including TGF-β1 and EGFR, which possibly could be involved in the development of orofacial cleft." (PMID 34393631, 2021). "Two of these possible factors, which could possibly play a role in the development of orofacial clefts, are transforming growth factor beta 1 (TGF-β1) and epidermal growth factor receptor (EGFR)." (PMID 34393631, 2021).
osteomyelitis (1 paper, 2024). An acute or chronic inflammation of the bone and its structures due to infection with pyogenic bacteria. "It was reported that S. aureus internalization into osteoblasts plays a critical role in the persistence and recurrence of osteomyelitis, and the EGFR/FAK and c-Src signaling pathways mediate osteoblastic S. aureus internalization." (PMID 38560264, 2024).
otitis media (1 paper, 2012). Inflammation of the anatomical structures of the middle ear, which is most often caused by an infectious process. "There were no ≥grade-3 RT-related toxicities in patients treated with brain RT alone, but 4 patients experienced major toxicities (grade-3 acneiform rash in 2 patients, grade-3 oral mucositis in 1 patient, and grade-3 otitis media in 1 patient) during the course of concurrent EGFR TKI use." (PMID 23110940, 2012).
ovarian disease (1 paper, 2019). "Epidermal Growth Factor Receptor (EGFR) is, for the most part, deregulated and over-communicated in ovarian disease, which islegitimately connected with STAT3 enactment that prompts the collection of hostile to apoptotic occasions and along these lines, docetaxelmedicate obstruction happens." (PMID 31285646, 2019).
ovarian dysfunction (1 paper, 2026). The inability of the ovaries to function. "In KGN cells modeling LPD and POF phenotypes, cellular experiments confirmed that BaP downregulated EGFR and ESR1 expression while upregulating STAT3 expression, thereby supporting the reliability of these targets in BaP-induced ovarian dysfunction." (PMID 41828455, 2026).
ovarian epithelial tumor (1 paper, 2012). A benign, borderline, or malignant tumor that originates from the surface epithelium of the ovary. "There is abundant evidence that EGFR activation drives cellular processes linked to ovarian epithelial tumor development, tumor cell survival and metastasis; and clinical trials are ongoing to target ErbB family receptors for epithelial ovarian cancer therapy." (PMID 23155381, 2012).
Pasteurella multocida infection (1 paper, 2023). "It was also found that P0910 and ΔOmpH in Pasteurella multocida infection activated the expression of ropE, HSPBP1, FERH, ATP10A, ABCA13, RRP7A, IL-10, IFN-γ, IL-17A, EGFR and dnaJ." (PMID 36977260, 2023).
Pca (1 paper, 2013). "Considering the relationship of these SNPs with other cancers and the function of angiogenesis for the EGFR gene, we inferred that the SNPs we proposed might be associated with the metastasis of Pca to the kidney, breast and other viscera." (PMID 24223781, 2013). "As one of the significant genes, EGFR was proven to be important in PCa risk." (PMID 24223781, 2013). "In addition, the results suggested the association with PCa risk was mainly focused on EGFR." (PMID 24223781, 2013). "Combining natural selection, gene-based pathway analysis, and other associated analysis, we proposed that the pathway was significantly associated with PCa risk, in which the mutation of EGFR, ERBB2, PTK2, RAF1, and related SNPs in the genes might be the key link in the evolution of the cancer." (PMID 24223781, 2013). "In this study, it is suggested many genes in the pathway are significant, especially EGFR, ERBB2, PTK2, and RAF1, which were not only associated with PCa risk, but also under natural selection." (PMID 24223781, 2013). "With these haplotypes and gene analyses on the positive selection loci, the EGFR was identified again, so we suggested the gene might potentially play an important role in the development and progression of PCa." (PMID 24223781, 2013). "Therefore, specific anti-EGFR monoclonal antibodies could inhibit cell growth and downregulate the related genes, which could reduce the development of PCa." (PMID 24223781, 2013). "After combining all the genes we proposed 4 genes (EGFR, ERBB2, PTK2, and RAF1) with five SNPs (rs11238349, rs17172438, rs984654, rs11773818, and rs17172432) as the key factors influencing PCa." (PMID 24223781, 2013). "In summary, we concluded from our analysis that four genes (EGFR, ERBB2, PTK2 and RAF1) undergoing positive selection might be important in the regulation of PCa development via various mechanisms." (PMID 24223781, 2013). "In addition, combined with the natural selection, it seems that 4 genes (EGFR, ERBB2, PTK2, and RAF1) with five SNPs (rs11238349, rs17172438, rs984654, rs11773818, and rs17172432) especially rs17172432, might be pivotal factors in the development of PCa." (PMID 24223781, 2013).
pemphigus vulgaris (1 paper, 2014). Pemphigus is a group of chronic autoimmune skin diseases characterized by blister formations on the outer layer of the skin and the mucous membranes. "In addition, in the autoimmune cutaneous disease pemphigus vulgaris, the body produces autoantibodies that can induce EGFR activation and ERK phosphorylation, leading to activation of caspase-3." (PMID 25144461, 2014).
penile tumours (1 paper, 2011). "Anti-EGFR therapies such as monoclonal antibodies (cetuximab) or small molecule tyrosine kinase inhibitors (TKI) (erlotinib, gefitinib and lapatinib) could be employed particularly to treat HPV-negative penile tumours." (PMID 21407808, 2011).
periapical granuloma (1 paper, 2024). Chronic nonsuppurative inflammation of periapical tissue resulting from irritation following pulp disease or endodontic treatment. "Before assessing the localization of EGFR and EGFRPhospho and TCPTP in cases of periapical granuloma, it is crucial to establish its role in healthy control tissues." (PMID 39446923, 2024).